ITLN1 (intelectin 1)
Diseases named in the same sentence as ITLN1 in open-access papers (continued):
Sharing a sentence is not in itself a finding about the gene and the disease.
ovarian tumor (1 paper, 2020). "We hypothesized that high ITLN1 levels may suppress ovarian tumor growth by increasing adipocytes’ glucose uptake in the omental microenvironment, thereby decreasing the glucose available to neighboring OC cells." (PMID 32669559, 2020).
pancreatic cancer (1 paper, 2022). "Circulating ITLN1 levels also seem to be increased in pancreatic cancer patients compared with healthy controls." (PMID 35186726, 2022).
prostate (1 paper, 2024). "Significantly, our results suggest that ITLN-1 deficiency may contribute to the development of BPH, potentially through the upregulation of proinflammatory factors and subsequent prostate inflammation." (PMID 38519941, 2024).
prostate hypertrophy (1 paper, 2024). "Our findings also highlight the protective effect of ITLN-1 against TP-induced prostate hypertrophy, as evidenced by the reduction in prostate weight and PAP levels." (PMID 38519941, 2024).
Sepsis (1 paper, 2023). Sepsis is defined as life-threatening organ dysfunction caused by a dysregulated host response to infection. "Background and Objectives: Omentin-1, also known as intelectin-1, is a novel adipokine with anti-inflammatory activities implicated in inflammatory diseases and sepsis." (PMID 37241065, 2023).
tumor (34 papers, 2011 to 2025). "Loss of ITLN1 was correlated to a more aggressive tumor phenotype and worse prognosis, suggesting its relevance as both a prognostic marker and therapeutic target." (PMID 41149627, 2025). "Our study revealed that ITLN1 expression was significantly downregulated in HCC tissues compared to adjacent non-tumor tissues, and its reduced expression was associated with poor overall survival." (PMID 41218553, 2025). "ITLN-1 is a secreted soluble glycoprotein which has been reported to be associated with the occurrence and development of various tumor types." (PMID 38050235, 2023). "Clinically, ITLN1 expression was strongly associated with a favorable tumor phenotype." (PMID 41149627, 2025). "Studies have shown that ITLN-1 has antimicrobial, antiinflammatory, and immunomodulatory effects, which has been reported to be associated with the occurrence and development of various tumor types." (PMID 38050235, 2023). "It encodes a lectin known as intelectin-1 or omentin-1, which acts as a tumor suppressor in CRC." (PMID 33919332, 2021). "This study extends our knowledge about the regulation of tumor suppressive genes associated with the progression of NB, and suggests that ITLN1 may be of potential values as a novel therapeutic target for NB." (PMID 25889839, 2015). "Consequently, the high levels of circulating ITLN1 might be determined by the tumor and by the cancer-associated weight loss in gastrointestinal cancer." (PMID 35186726, 2022). "We evaluated ITLN1 expression in paired tumor and adjacent non-tumor tissues from 95 patients in Tongji cohort to validate these findings." (PMID 41218553, 2025). "Positive correlations were observed between the HOMA-IR and ITLN1 and CD295 SNPs, as well as a positive correlation between LEP and tumor grade, establishing connections between genetic variants and metabolic phenotypes." (PMID 41221514, 2025). "Advanced single-cell RNA sequencing should be employed to map ITLN1 expression and its receptors within the tumor microenvironment, clarifying the cellular origin and targets of omentin-1 signaling across gastrointestinal malignancies." (PMID 41149627, 2025). "Functionally, ITLN1 functioned as a tumor suppressor through the activation of the ERK1/2 signaling pathway, leading to the inhibition of HCC growth." (PMID 41218553, 2025). "Western blot analysis in 18 randomly selected paired tissues from the Tongji cohort further confirmed the reduced ITLN1 protein levels in tumor tissues." (PMID 41218553, 2025). "We further confirmed the downregulation of ITLN1 protein levels in tumor tissues from these 18 patients using immunohistochemistry." (PMID 41218553, 2025). "In multivariate Cox regression adjusting for tumor burden, fibrosis, and vascular features, high ITLN1 remained an independent predictor of improved outcome, halving the hazard of death and recurrence (HR ≈ 0.5)." (PMID 41149627, 2025). "Comprehensive cohort studies that concurrently measure circulating omentin-1, tumor-localized ITLN1 expression, its chaperone protein TMEM207, and detailed patient metabolic profiles are thus needed." (PMID 41149627, 2025). "Tumor clinical stage T II and positive LN involvement, as well as tumor histologic grade III, were associated with CD295 rs6700986 CC and CT genotypes, as well as ITLN1 rs952804 mutant CT cases (p ≤ 0.05)." (PMID 41221514, 2025). "Low ITLN1 levels correlated with larger tumor size (≥5 cm), poor differentiation, capsular invasion, cirrhosis, and vascular infiltration, all hallmarks of biologically aggressive disease." (PMID 41149627, 2025). "The decreased expression of ITLN1 is in conjunction with an unfavorable outlook for patients, suggesting a potential tumor-suppressive role in HCC." (PMID 41218553, 2025).
tumor (continued). "Further research in an orthotopic xenograft tumor model indicated that ITLN1 overexpression markedly inhibited orthotopic liver tumor growth." (PMID 41218553, 2025). "Our research revealed a downregulation of ITLN1 expression in HCC tissues compared to adjacent non-tumor tissues, and this downregulation corrected with an unfavorable prognosis for patients with HCC." (PMID 41218553, 2025). "In gastrointestinal cancers, intelectin-1 gene expression has been reported to be higher in tumor tissues compared to adjacent normal tissues." (PMID 41149627, 2025). "The expression of ITLN-1 was 454.8 times higher in tumor-adjacent normal liver tissues than in corresponding cancer tissues." (PMID 38050235, 2023). "The mRNA level of ITLN-1 in tumor tissues was significantly lower than in adjacent normal liver tissues (P < .05)." (PMID 38050235, 2023). "Kaplan–Meier analysis showed that the OS (P < .001) and DFS (P < .001) of patients with high tumor expression of ITLN-1 were significantly better than those of patients with low ITLN-1 expression in tumor tissues." (PMID 38050235, 2023). "In this study, we found that the expression of ITLN-1 was significantly lower in HCC tissues than in adjacent non-tumor tissues." (PMID 38050235, 2023). "Gene microarray analysis showed that the expression of Intelectin-1 (ITLN-1) in tumor-adjacent normal liver tissue was 454.8 times higher than in the corresponding cancer tissue." (PMID 38050235, 2023). "The expression of ITLN-1 mRNA in tumor tissues was significantly lower than in adjacent non-tumor tissues (P < .01)." (PMID 38050235, 2023). "This work would have to further confirm and take account of the possible tumor-specific direction of change in ITLN1." (PMID 35186726, 2022). "Future research should aim to identify the source of ITLN1 variability, to understand the differences in ITLN1 between distinct tumor types, and to further explore the signaling pathways through which this adipokine influences cancer biology." (PMID 35186726, 2022). "In gastrointestinal cancer, ITLN1 was increased in tumor tissue compared with adjacent healthy tissue and elevated in the visceral adipose tissue of patients compared with controls." (PMID 35186726, 2022). "In contrast, another recent study showed that the tumor suppressor ITLN1 promoted HNF4A expression by repressing NF-κB in GC28, and high HNF4A expression showed improved survival outcomes." (PMID 33710810, 2021). "We found a significant decrease in tumor growth rates, significant lower ascites volumes, and significantly higher circulating ITLN1 levels and lower glucose levels in ITLN1-treated mice compared with control mice." (PMID 32669559, 2020). "We further confirmed that secretory ITLN1 inhibited the growth, invasion, and metastasis of NB cells in vitro and in vivo, suggesting the tumor suppressive roles of ITLN1 in NB." (PMID 25889839, 2015). "Nkx3.1 is highly expressed in the prostate, where it is believed to function as a tumour repressor gene, and regulates Itln1 expression in prostate epithelial cells." (PMID 21324158, 2011). "Their data suggested that preserved ITLN1 may reflect or contribute to a less invasive tumor phenotype, and supported its use as a molecular marker for outcome prediction in metastatic colorectal cancer." (PMID 41149627, 2025). "Although ITLN1 overexpression led to only a modest increase in the proportion of tumor cells in the G0/G1 phase, the marked reduction in proliferation suggests that additional mechanisms may be involved." (PMID 41218553, 2025). "CDH5, ID1, H2BC10, and ITLN1 were common DEGs in the tumor and stroma areas." (PMID 40422184, 2025). "The ITLN1 mRNA level was markedly downregulated in tumor tissues from patients in Tongji cohort." (PMID 41218553, 2025). "Furthermore, the downregulation of mesothelial cell-derived ITLN1 in the omental tumor microenvironment has been demonstrated to facilitate OC progression." (PMID 40563510, 2025).
tumor (continued). "While the function of ITLN1 in these cancers is unknown, some of the evidence presented above would suggest that higher local tumor levels may be a good prognostic indicator." (PMID 35186726, 2022). "Since circulating ITLN1 levels are highly variable and differ between cancer types, the local tumor production of ITLN1 could be more relevant in determining malignant behavior." (PMID 35186726, 2022). "Given that circulating ITLN1 varies between different types of cancer, the local level or the tumor production of ITLN1 may be more important than the circulating level in contributing to malignant behavior." (PMID 35186726, 2022). "Several studies also evaluated tissue and tumor expression of ITLN1." (PMID 35186726, 2022). "The suppressor effect can only be observed in the presence of FBS, suggesting that ITLN1 may inhibit tumor invasion by counteracting mediators in the serum." (PMID 32669559, 2020). "We next investigated the efficacy of ITLN1 against tumor growth and metastasis in vivo." (PMID 25889839, 2015). "In addition, rescue experiments in ITLN1 over-expressed or silenced NB cells showed that restoration of NDRG2 expression prevented the tumor cells from ITLN1-mediated changes in these biological features." (PMID 25889839, 2015). "Immunohistochemical staining revealed that ITLN1 was expressed in the tumor cells of NB tissues." (PMID 25889839, 2015). "Finally, we conducted a gene network analysis of the DEFA gene and found that there were tumor-suppressor-related genes associated with DEFA, including FGF21 and ITLN1, as well as tumor-promoting genes associated with DEFA, including GNB3, CRB2, DIO3, HPD, and Dll3." (PMID 41009818, 2025). "For Western blot results, the tumor sizes of the 3 pairs of specimens were 2.3 cm, 4.0 cm, and 5.1 cm, respectively, including 1 case at stage T1, 1 case at stage T2, and 1 case at stage T3.The results showed that the expression of ITLN-1 was higher in the adjacent tissues." (PMID 38050235, 2023). "Moreover, restoration of NDRG2 expression prevented the NB cells from ITLN1-mediated changes in the growth, invasion, and metastasis, suggesting that ITLN1 may exert its tumor suppressive functions, at least in part, through up-regulating NDRG2 in NB." (PMID 25889839, 2015). "Mapping tumor subpopulations onto this trajectory revealed that C0 NAP1L1+ TCs and C2 MKI67+ TCs generally occupied the early pseudotime segment, C3 ITLN1+ TCs were situated in the intermediate region, and C1 CA2+ TCs were primarily found in the late segment." (PMID 40842994, 2025). "Matched tumor and adjacent normal mucosa from 24 CRC patients revealed approximately 5-fold higher ITLN1 mRNA in the malignant tissue, accompanied by markedly increased protein levels as shown by immunohistochemistry." (PMID 41149627, 2025). "SERPINA1, ITLN1, and REG4 upregulation in primary tumor tissues was negatively correlated with distant metastasis, indicating a protective effect on prognosis in patients with CRC." (PMID 38083905, 2023). "Pan-cancer expression analysis results showed that ITLN1, TSPAN11, CXCL13, and GPRC5B were downregulated and TIMP1 was upregulated in most tumor samples, including COAD, which was consistent with the results of the TCGA and GEO cohorts." (PMID 33579281, 2021). "This suggests that the expression level of ITLN1 in mesothelial cells in HGSC patients is regulated by these cytokines in an autocrine and paracrine manner in the tumor microenvironment." (PMID 32669559, 2020). "HEPACAM2, ITLN1, LGALS2, MUC12, and NXPE1 presented a sequentially descending trend in expression with tumor progression." (PMID 29659199, 2018). "On the other hand, stable knockdown of ITLN1 in SH-SY5Y cells resulted in increased growth and tumor weight of subcutaneous xenograft tumors in athymic nude mice, and more lung metastatic colonies, than those stably transfected with sh-Scb." (PMID 25889839, 2015).
tumor (continued). "Stable transfection of ITLN1 into SGC-7901 cells resulted in decreased growth and tumor weight of subcutaneous xenograft tumors in athymic nude mice, when compared to those stably transfected with empty vector (mock)." (PMID 25965823, 2015). "On the other hand, stable knockdown of ITLN1 in SGC-7901 cells resulted in increased growth and tumor weight of subcutaneous xenograft tumors in athymic nude mice, and more lung metastatic colonies, when compared to those stably transfected with sh-Scb." (PMID 25965823, 2015). "Stable transfection of ITLN1 into SH-SY5Y cells resulted in decreased growth and tumor weight of subcutaneous xenograft tumors in athymic nude mice, when compared to those stably transfected with empty vector (mock)." (PMID 25889839, 2015). "Although the mechanistic pathways were not explored in this study, the authors referenced ITLN1’s known roles in modulating HNF4α and β-catenin signaling as possible avenues for its anti-tumor function." (PMID 41149627, 2025). "We classified a total of 7,759 tumor cells into separate subpopulations based on their DEGs and designated each cluster according to its most prominently expressed marker gene: C0 NAP1L1+ TCs, C1 CA2+ TCs, C2 MKI67+ TCs, and C3 ITLN1+ TCs." (PMID 40842994, 2025). "Moreover, the CytoTRACE2-Potency analysis characterized all tumor cell subpopulations, indicating that the majority of C1 CA2+ TCs and C3 ITLN1+ TCs were differentiated." (PMID 40842994, 2025). "A negative correlation was observed between ITLN1 and tumor grade and a positive correlation with age." (PMID 41221514, 2025). "Taken together, the results of this study indicate that ITLN-1 may inhibit the occurrence and development of HCC, thus playing the role of a tumor suppressor gene." (PMID 38050235, 2023). "However, in this study, we did not investigate the hepatokine function of ITLN1 in the tumor microenvironment." (PMID 41218553, 2025). "While numerous studies on IRF1 have primarily focused on its effects on tumor invasion and the immune microenvironment, we conducted a "rescue" experiment to evaluate the correlation between IRF1 and HCC proliferation, specifically investigating the involvement of ITLN1 in this regulatory process." (PMID 41218553, 2025). "In addition, ITLN1 increased recombinant glucose transporter-4 (GLUT4) production in adipocytes, which contributed to increased glucose uptake by adiposes and decreased glucose uptake by tumor cells, thereby the proliferation of OC cells was inhibited." (PMID 36268019, 2022). "Moreover, the downregulation of ITLN1 in CAMs inhibited the insulin-dependent glucose uptake in mature adipocytes via suppressing the expression of GLUT4, which increased the glucose available to OC cells and promote the tumor growth." (PMID 36268019, 2022). "In addition, we found that ITLN1 induced the KLF4 expression via inactivation of PI3K/AKT signaling, which was required for ITLN1-mediated up-regulation of NDRG2 in NB cells, suggesting the tumor suppressive roles of ITLN1/KLF4/NDRG2 axis in the tumorigenesis of NB." (PMID 25889839, 2015). "This suggests that decreased levels of ITLN1 allow LTF to downregulate GLUT4 and decrease glucose uptake in adipocytes without opposition, leading to enhanced tumor cell growth." (PMID 32669559, 2020).